H2AB1 (H2A.B variant histone 1)
Description:
Atypical histone H2A which can replace conventional H2A in some nucleosomes and is associated with active transcription and mRNA processing. Nucleosomes wrap and compact DNA into chromatin, limiting DNA accessibility to the cellular machineries which require DNA as a template. Histones thereby play a central role in transcription regulation, DNA repair, DNA replication and chromosomal stability. Nucleosomes containing this histone are less rigid and organize less DNA than canonical nucleosomes in vivo. They are enriched in actively transcribed genes and associate with the elongating form of RNA polymerase. They associate with spliceosome components and are required for mRNA splicing.
Synonyms: H2A.B; H2A.Bbd; H2AFB1; H2A.B.2
Tractability: No criterion of Open Targets' tractability assessment is met for any kind of drug.
Gene: Protein-coding gene on chromosome X (154,884,972 to 154,885,558, forward strand). Ensembl gene ENSG00000274183.
Subcellular location: Nucleus; Chromosome
Pathways (Reactome):
Gene expression (Transcription): B-WICH complex positively regulates rRNA expression; DNA methylation; ERCC6 (CSB) and EHMT2 (G9a) positively regulate rRNA expression; MLL4 and MLL3 complexes regulate expression of PPARG target genes in adipogenesis and hepatic steatosis; NoRC negatively regulates rRNA expression; PRC2 methylates histones and DNA; RNA Polymerase I Promoter Escape; RNA Polymerase I Promoter Opening; RUNX1 regulates genes involved in megakaryocyte differentiation and platelet function; RUNX1 regulates transcription of genes involved in differentiation of HSCs; Regulation of endogenous retroelements by KRAB-ZFP proteins; Regulation of endogenous retroelements by Piwi-interacting RNAs (piRNAs); Regulation of endogenous retroelements by the Human Silencing Hub (HUSH) complex; SIRT1 negatively regulates rRNA expression; Transcriptional regulation by small RNAs
Chromatin organization: CHD1 and CHD2 subfamily; CHD6, CHD7, CHD8, CHD9 subfamily; ChAHP complex assembly; Interaction of NuRD complexes with transcription factors; NuRD complex assembly; RMTs methylate histone arginines
Cell Cycle: Condensation of Prophase Chromosomes; Deposition of new CENPA-containing nucleosomes at the centromere; Inhibition of DNA recombination at telomere; Packaging Of Telomere Ends
DNA Repair: Cleavage of the damaged purine; Cleavage of the damaged pyrimidine; Recognition and association of DNA glycosylase with site containing an affected purine; Recognition and association of DNA glycosylase with site containing an affected pyrimidine
Signal Transduction: Activated PKN1 stimulates transcription of AR (androgen receptor) regulated genes KLK2 and KLK3; Estrogen-dependent gene expression; Formation of the beta-catenin:TCF transactivating complex; Pre-NOTCH Transcription and Translation
Cellular responses to stimuli: DNA Damage/Telomere Stress Induced Senescence; Oxidative Stress Induced Senescence; Senescence-Associated Secretory Phenotype (SASP)
Developmental Biology: Activation of anterior HOX genes in hindbrain development during early embryogenesis; Chromatin modifications during the maternal to zygotic transition (MZT); Transcriptional regulation of granulopoiesis
Immune System: FXIIa activates plasma kallikrein-kinin system
and 7 more pathways
Gene Ontology:
Molecular function: structural constituent of chromatin; DNA binding; protein heterodimerization activity
Biological process: mRNA processing; nucleosome assembly; heterochromatin formation
Cellular component: chromosome; euchromatin; nucleosome; nucleus
Homologues: Orthologues: chimpanzee H2AB3 (97% identical), macaque H2AB1 (87% identical), macaque H2AB2 (87% identical), mouse H2ab3 (56% identical), rat H2ab3 (56% identical), mouse H2ab1 (55% identical), mouse H2ab2 (50% identical), Drosophila melanogaster His2A:CG31618 (42% identical), Drosophila melanogaster His2A:CG33808 (42% identical), Drosophila melanogaster His2A:CG33814 (42% identical), Drosophila melanogaster His2A:CG33817 (42% identical), Drosophila melanogaster His2A:CG33820 (42% identical), and 15 more. Paralogues in human: H2AB2 (99% identical), H2AB3 (99% identical), H2AC21 (44% identical), H2AL1Q (44% identical), H2AX (44% identical), H2AC6 (43% identical), H2AJ (43% identical), H2AC11 (43% identical), H2AC12 (43% identical), H2AC13 (43% identical), H2AC14 (43% identical), H2AC15 (43% identical), and 15 more.
Diseases named in the same sentence as H2AB1 in open-access papers:
H2AB1 is named in the same sentence as 24 diseases in open-access papers, as found by Europe PMC text mining. Sharing a sentence is not in itself a finding about the gene and the disease. The quoted sentences say what the papers report.
allergic rhinitis (2 papers, 2018 to 2024). Inflammation of the nasal mucous membranes caused by an IgE-mediated response to external allergens. "We herein examined the importance of H2-Eb1 and H2-Ab1 in the susceptibility of mice to allergic rhinitis (AR) by developing double-gene (H2-Eb1+H2-Ab1) knockout mice." (PMID 30372475, 2018). "Relevant animal experiments have demonstrated that H2-Eb1 and H2-Ab1 affects the development of allergic rhinitis; the expression of MHC II in the renal tubular affects renal fibrosis; and MHC II plays crucial roles in tumor prognosis and cancer metastasis." (PMID 39010027, 2024).
atherosclerosis (1 paper, 2013). A disease characterized by the build-up of fatty material and calcium deposition in the arterial wall resulting in partial or complete occlusion of the arterial lumen. "Genes encoding MHC molecules such as H2-Ab1 (FC −2.32) and H2-Eb1 (FC −2.36), which have been implicated in atherosclerosis, were down-regulated in the spleens of mice, thus suggesting that OPP was able to attenuate the inflammatory response brought about by the atherogenic diet." (PMID 22527284, 2013).
colitis (1 paper, 2022). Inflammation of the colon. "Taken together, NPP7 KO mice are more susceptible to induction of intestinal inflammation and proinflammatory as well as protective factors (e.g. ceramide, S1P, osteopontin and H2-AB1) are differentially expressed in NPP7 KO mice already before a colitis-inducing challenge." (PMID 36741374, 2022).
diabetic nephropathy (1 paper, 2022). "Among these proteins, high levels of fibrinogen proteins (Fgg and Fga), cathepsin proteins (ctss and ctsa), H2-Ab1 and prcp were considered risk factors for diabetic nephropathy and the predictors of urinary protein progression." (PMID 36104729, 2022).
Hepatic fibrosis (1 paper, 2021). The presence of excessive fibrous connective tissue in the liver. "In the “hepatic fibrosis” pathway, eight fibrogenic genes (Pparg, Krt8, H2-Ab1, H2-Aa, Nqo1, Il33, and Ltb) are upregulated, and one gene (Serpina1c) is downregulated." (PMID 33916843, 2021).
melanoma (1 paper, 2023). A malignant, usually aggressive tumor composed of atypical, neoplastic melanocytes. "M1/M2 phenotypes of TAMs in the melanomas of WT and Colec11–/– mice were further evaluated by IHC costaining of CD206/CD68 or H2-Ab1/CD68." (PMID 36883567, 2023).
tumor (10 papers, 2022 to 2025). "Of note, a heatmap based on GSEA showed several tumor-associated immune checkpoints, such as H2-Ab1, CD86, CD80, and CD276, CD274 (Pdl1), were downregulated upon Prmt3 deletion." (PMID 40050608, 2025). "Lymphocyte related genes (CD3, CD8), B cell receptor related genes (CD40, CD79a), major histocompatibility complex (MHC) related genes (H2-Ab1, Ciita) were significantly downregulated in the tumor tissues of BDL mice." (PMID 38951890, 2024). "The increased expression of Stat1, Ido1, and H2ab1 suggested that the IFNγ signal in the tumor was upregulated and accompanied by elevated IFNγ expression in CTLs." (PMID 36793737, 2023). "Notably, only M002-treated CD4+ T cells and cluster 2 cells, but not saline-treated counterparts, interacted with tumor cells via MHCII pathways, specifically H2Ab1-Cd4 interactions." (PMID 39885128, 2025).
cancer (4 papers, 2022 to 2025). A tumor composed of atypical neoplastic, often pleomorphic cells that invade other tissues. "Some ID8 cancer cells expressed low amounts of H2-Ab1 (MHC-II), but in STOSE tumors, it was attributed only to the immune population." (PMID 36311166, 2022).
immune dysfunction (1 paper, 2025). "Similarly, H2-Ab1 knockout has been linked to immune dysfunction." (PMID 40791429, 2025).
infection (1 paper, 2022). The state of being infected such as from the introduction of a foreign agent such as serum, vaccine, antigenic substance or organism. "In T. regenti-infected spinal cords, we recorded striking upregulation of Cd74, H2-Aa, H2-Ab1, and other members of the MHC II pathway throughout the infection." (PMID 35120185, 2022).
neurodegenerative disease (1 paper, 2023). A disorder of the central nervous system characterized by gradual and progressive loss of neural tissue and neurologic function. "H2-Ab1 is part of a hub gene network associated with aging and neurodegenerative disease." (PMID 37894838, 2023).
H2AB1 also shares sentences with these, for which no sentence is quoted: amyloidosis (1 paper); Arthritis (1); autoimmune disease (1); dermatitis (1); experimental autoimmune encephalomyelitis (1); Insulin resistance (1); multiple sclerosis (1); Obesity (1); Parkinson disease (1); pulmonary arterial hypertension (1); renal fibrosis (1); Stroke (1); viral infection (1).